PARD6G (par-6 family cell polarity regulator gamma)
Description:
Adapter protein involved in asymmetrical cell division and cell polarization processes. May play a role in the formation of epithelial tight junctions. The PARD6-PARD3 complex links GTP-bound Rho small GTPases to atypical protein kinase C proteins (By similarity).
Synonyms: PAR-6G; PAR6gamma
Tractability: Antibody: its Gene Ontology location is reachable by antibodies, with high confidence; UniProt places it where antibodies can reach, with medium confidence; the Human Protein Atlas places it where antibodies can reach. PROTAC: ubiquitination databases record sites on it; its protein half-life has been measured.
Gene: Protein-coding gene on chromosome 18 (80,157,232 to 80,247,514, reverse strand). Ensembl gene ENSG00000178184.
Subcellular location: Cytoplasm; Cell membrane; Cell junction, tight junction
Subcellular location (Human Protein Atlas): Plasma membrane
Pathways (Reactome):
Cell-Cell communication: Tight junction interactions
Gene Ontology:
Molecular function: protein binding
Biological process: centrosome cycle; establishment or maintenance of cell polarity; regulation of cellular localization
Cellular component: apical plasma membrane; cell cortex; cytosol; nucleus; plasma membrane; tight junction; bicellular tight junction; cytoplasm
Genetic constraint (gnomAD): Loss-of-function variants: 6 observed, 7.53 expected, observed/expected ratio (o/e) 0.8, 90% interval 0.44 to 1.54. That is too few expected variants to judge how well the gene tolerates losing a copy. Missense variants: 546 observed, 493.88 expected, observed/expected ratio (o/e) 1.11, 90% interval 1.03 to 1.19. Synonymous variants: 287 observed, 231.61 expected, observed/expected ratio (o/e) 1.24, 90% interval 1.12 to 1.37.
Homologues: Orthologues: chimpanzee PARD6G (99% identical), macaque PARD6G (99% identical), guinea pig PARD6G (80% identical), dog PARD6G (80% identical), pig PARD6G (80% identical), rat Pard6g (80% identical), mouse Pard6g (78% identical), tropical clawed frog pard6g (70% identical), zebrafish pard6gb (67% identical), Drosophila melanogaster par-6 (44% identical), Caenorhabditis elegans par-6 (41% identical). Paralogues in human: PARD6B (56% identical), PARD6A (48% identical).
Diseases named in the same sentence as PARD6G in open-access papers:
PARD6G is named in the same sentence as 7 diseases in open-access papers, as found by Europe PMC text mining. Sharing a sentence is not in itself a finding about the gene and the disease. The quoted sentences say what the papers report.
breast carcinoma (1 paper, 2020). "Hypermethylation and downregulation of PARD6G was concluded to be involved in DNA repair mechanisms in bisphenol A (BPA, a xenoestrogen) exposed human-derived breast cancer epithelial cells." (PMID 33008348, 2020).
lung carcinoma (1 paper, 2025). "PARD6G, a parapolar protein, is involved in the regulation of cell polarity, and studies have demonstrated that its differential expression among subtypes of lung cancer has a role as a potential marker; however, its function in GC has not yet been explored in depth [PMID: 32360590]." (PMID 40191191, 2025).
Prader-Willi syndrome (1 paper, 2022). "PofOm enrichment at SoC-CpGs is driven by a large PofOm region spanning 6 CpGs on chr15 at IGF1R; along with two singleton PofOm SoC-CpGs, one on chr18 close to PARD6G and the other in the Prader-Willi syndrome-associated imprinted region neighbouring MAGEL2, also on chr15." (PMID 35188105, 2022).
PARD6G also shares sentences with these, for which no sentence is quoted: Cirrhosis (1 paper); craniorachischisis (1); lung adenocarcinoma (1); lung squamous cell cancer (1).